SNORD115-35 (small nucleolar RNA, C/D box 115-35)
Synonyms: HBII-52-35
Gene: Small nucleolar RNA gene on chromosome 15 (25,234,247 to 25,234,328, forward strand). Ensembl gene ENSG00000201992.
Gene Ontology:
Biological process: RNA processing
Cellular component: nucleolus
Homologues: Orthologues: chimpanzee SNORD115 (100% identical), dog SNORD115 (63% identical). Paralogues in human: SNORD115-16 (96% identical), SNORD115-11 (95% identical), SNORD115-13 (95% identical), SNORD115-29 (95% identical), SNORD115-36 (95% identical), SNORD115-43 (95% identical), SNORD115-10 (94% identical), SNORD115-12 (94% identical), SNORD115-21 (94% identical), SNORD115-22 (94% identical), SNORD115-26 (94% identical), SNORD115-31 (94% identical), and 37 more.